OXTR (oxytocin receptor)
Diseases named in the same sentence as OXTR in open-access papers (continued):
Sharing a sentence is not in itself a finding about the gene and the disease.
postpartum hemorrhage (2 papers, 2022 to 2024). Hemorrhage defined as a blood loss in excess of 500 mL after vaginal delivery or more than 1000 mL after a cesarean delivery. "Further, we showed that OXTR methylation is associated with higher postpartum blood loss and need for postpartum oxytocin administration, the first line treatment for postpartum hemorrhage." (PMID 38862858, 2024). "In sum, we provide evidence that a common OXTR variant is associated with greater risk for postpartum hemorrhage." (PMID 36447139, 2022). "Both genetic and epigenetic factors related to the oxytocin receptor are associated with risk of postpartum hemorrhage, but a mechanism relating these factors to oxytocin receptor activity in myometrium remains unclear." (PMID 38862858, 2024). "We provide evidence of a risk allele in the oxytocin receptor gene that may be involved in the development of postpartum hemorrhage among participants undergoing vaginal birth, particularly among those with fewer risk factors." (PMID 36447139, 2022). "Here, using myometrium samples collected from women undergoing unlabored cesarean section, we provide evidence of a genetic by epigenetic interaction regulating OXTR expression in pregnant myometrium which may explain differential risk of postpartum hemorrhage associated with SNP rs53576." (PMID 38862858, 2024). "We demonstrated that a common genetic variant in the third intron of OXTR (rs53576) confers risk for postpartum hemorrhage, particularly in women without other common risk factors." (PMID 38862858, 2024). "Nonetheless, these results represent a significant advance in our understanding of how genetic variation in OXTR might lead to oxytocin sensitivity during pregnancy and postpartum hemorrhage." (PMID 38862858, 2024). "However, how DNA methylation and genetic factors interact in regulating OXTR expression or conferring risk for postpartum hemorrhage is not yet established." (PMID 38862858, 2024).
Prader-Willi syndrome (2 papers, 2022 to 2023). "In the Magel2-deficient mouse, mouse models of Prader-Willi syndrome, the number of oxytocin neurons and the oxytocin receptor-expressing astrocytes were reduced in the PVN." (PMID 37175953, 2023).
preeclampsia (2 papers, 2022 to 2024). Preeclampsia is a hypertensive disorder of pregnancy that is characterized by new-onset hypertension with proteinuria presenting after 20 weeks of gestation, and depending on mild or severe forms may initially present with severe headache, visual disturbances, and hyperreflexia. "Preliminary results of our own observational study DRKS0001771 (“Role of the oxytocin-receptor and the H2S-system in preeclampsia and HELLP-syndrome (NU-HOPE)”) confirm the dysregulation of endogenous H2S availability in pre-eclampsia, which has also been published previously." (PMID 35454132, 2022).
premature ejaculation (2 papers, 2021). A disorder characterized by persistent or recurrent ejaculation before or after penetration and before the person wishes it. "OXTR antagonists are of interest in the treatment of premature ejaculation (PE), and show promising preliminary results in animal models." (PMID 33737570, 2021).
Stroke (2 papers, 2020). Sudden impairment of blood flow to a part of the brain due to occlusion or rupture of an artery to the brain. "While this work suggests that the OXTR is a valid target for recovery of cerebrovascular insults, including stroke related to cognitive impairment and dementia, further mechanistic and validation studies are warranted, especially in reference to ischemic conditions." (PMID 33071746, 2020). "Potential effects of oxytocin receptor activation in cerebrovascular and post-stroke environment." (PMID 33071746, 2020). "Interestingly, the expression levels of oxytocin, oxytocin receptor, and BDNF were significantly decreased in the PFC examined at 8 weeks after stroke." (PMID 32010477, 2020). "Within this review, we have examined the foremost research on the functions of the OXTR at the cellular level and the consequences of this GPCR at the organismal level for both humans and animals, particularly with respect to vascular health and cerebrovascular dysfunction including stroke." (PMID 33071746, 2020).
vascular dementia (2 papers, 2020 to 2023). A degenerative vascular disorder affecting the brain. "In particular, there is therapeutic rationale for targeting the OXTR in the treatment and management of ischemic stroke and, potentially, vascular dementia." (PMID 33071746, 2020).
Williams syndrome (2 papers, 2022 to 2023). "The authors of that report predicted that there is an epigenetic control (based on DNA methylation) of the social behavior, as well as the influence of SNPs in the OXTR gene on the development of symptoms of Williams syndrome." (PMID 36835321, 2023). "Interestingly, apart from the effects of OXTR dysfunction on the pathomechanism of mucopolysaccharidoses (described in Section 5), the role of this receptor in the course of another genetic disorder, Williams syndrome, has been recently evaluated." (PMID 36835321, 2023).
acute myocardial infarction (1 paper, 2018). Necrosis of the myocardium, as a result of interruption of the blood supply to the area. "This and other aberrant physiological changes induced by acute myocardial infarction were decreased by oxytocin receptor antagonists, hinting to their potential therapeutic role." (PMID 30320228, 2018).
anovulation (1 paper, 2024). The absence of ovulation. "These variants of the OXTR gene were found to be related to the principal symptoms of PCOS, such as anovulation or oligovulation, hyperandrogenism, polycystic ovaries, and the increased risk for metabolic alterations." (PMID 38920985, 2024).
Arrhythmia (1 paper, 2018). Any cardiac rhythm other than the normal sinus rhythm. "Importantly, the incidence of arrhythmias was lower in the MI rats that received an oxytocin receptor antagonist either centrally (atosiban, 4.5 μg in 5 μl, i.c.v.)or intravenously (retosiban, 3 mg/kg)." (PMID 30320228, 2018).
behavior (1 paper, 2018). The internally coordinated responses (actions or inactions) of animals (individuals or groups) to internal or external stimuli, via a mechanism that involves nervous system activity. "Findings from the present study indicate the necessity of taking account of sex when investigating associations of the interactions of OXTR rs53576 genotypes and environmental factors with antisocial behavior." (PMID 29623035, 2018).
behavioural addictions (1 paper, 2023). "Our data confirmed the association of OXTR, DAT1 and SERT genes in processes related to behavioural addictions and might be of relevance to suggest possible biological predictors of altered behaviours and the eventual vulnerability to develop an IA." (PMID 38092954, 2023).
benign prostatic hyperplasia (1 paper, 2023). A non-cancerous nodular enlargement of the prostate gland. "So, targeting OXTR utilising oxytocin receptor antagonists can be clinically effective in the treatment of lower urinary tract symptoms associated with benign prostatic hyperplasia (LUTS/BPH)." (PMID 38001957, 2023).
binge eating disorder (1 paper, 2022). Recurrent episodes of over-eating. "OXT functioning is altered in patients with eating and weight disorders, and a variant of the oxytocin receptor gene (OXTR) has been associated with impulsive eating behavior as it is seen in patients with binge eating disorder (BED)." (PMID 36042529, 2022).
Bradycardia (1 paper, 2025). A slower than normal heart rate (in adults, slower than 60 beats per minute). "Selective chemogenetic excitation of OXTR-positive CVNs in the DMNX evoked a rapid and sustained bradycardia." (PMID 40769582, 2025). "Selective chemogenetic activation of OXTR+ CVNs in the DMNX evoked a rapid and sustained bradycardia." (PMID 40769582, 2025). "Selective chemogenetic excitation of OXTR+ CVNs in the DMNX—achieved by a combination of Cre- and flp-dependent DREADD expression—evoked a rapid and sustained bradycardia." (PMID 40769582, 2025). "The authors have presented solid evidence that OXT receptors (OXTR) are differentially expressed in cardiac vagal neurons with the DMV but not NA, and that chemogenetic excitation of these OXTR expressing neurons induced bradycardia." (PMID 40769582, 2025).
bulimia (1 paper, 2022). "Positive correlations have been identified between the G allele of the rs53576 oxytocin receptor and bulimia." (PMID 35888641, 2022).
Chronic colitis (1 paper, 2019). A chronic inflammatory disease of the large intestine (colon, cecum and rectum). "The results showed that the expressions of OXT and OXTR were relatively high in normal tissue, and the expressions in chronic colitis, tubular adenoma, and well-differentiated CAC decreased gradually." (PMID 31920487, 2019).
corneal opacities (1 paper, 2023). "Therefore, loss of OXTR may also contribute to corneal opacities by further reducing the cornea’s protection against stressors such as ultraviolet radiation." (PMID 37363400, 2023).
COVID-19 (1 paper, 2022). A disease caused by infection with severe acute respiratory syndrome coronavirus 2. "Maff also binds the oxytocin receptor promoter, which could contribute to sex differences in disease outcome – seen in COVID-19." (PMID 35123426, 2022).
dependence (1 paper, 2023). "Two additional genes, OAS3 (2’-5’-Oligoadenylate Synthetase 3) and OXTR (Oxytocin Receptor) show evidence in the NHGRI GWAS catalog for association with alcohol consumption and dependence, respectively." (PMID 37217680, 2023).
Depression Anxiety (1 paper, 2023). "Other polymorphisms within OXTR have been shown to be associated with differences in oxytocin receptor density in the brain and Depression Anxiety and Stress Scale (DASS) scores in humans." (PMID 37531334, 2023).
ductal carcinoma in situ (1 paper, 2025). "In ductal carcinoma in situ (DCIS)-associated myoepithelial cells, genes regulating laminin and oxytocin receptor function are downregulated, while tumor-promoting genes like CXCL12 and CXCL14 are upregulated." (PMID 40647432, 2025).
endometrial adenocarcinoma (1 paper, 2022). "Oxytocin (OT) was found to act as an antiproliferation regulator by activating the oxytocin receptor (OTR)/cAMP/PKA pathway in endometrial adenocarcinoma cells." (PMID 35011543, 2022).
esophageal adenocarcinoma (1 paper, 2023). A malignant tumor with glandular differentiation arising predominantly from Barrett mucosa in the lower third of the esophagus. "SNPs in the OXTR gene were associated with an increased risk of Barrett’s esophagus, a premalignant condition, and esophageal adenocarcinoma." (PMID 36835321, 2023).
fertility disorders (1 paper, 2013). "Given recent studies identifying functional OXTR in primate luteal cells and P inhibition of OT-signaling in bovine SLCs, further experiments could help identify causes of fertility disorders associated with luteal function in women." (PMID 23966904, 2013).
gastric cancer (1 paper, 2024). A primary or metastatic malignant neoplasm involving the stomach. "However, it was disappointing that regulation of estrogen receptor α66 (ER-α66), estrogen receptor β (ER-β), and oxytocin receptor (OTR) contributed inversely negative effects on anti-gastric cancer cells." (PMID 38268762, 2024).
gastroparesis (1 paper, 2012). Paralysis of the muscles of the stomach wall resulting in delayed emptying of the gastric contents into the small intestine. "Previous studies have shown that the oxytocin receptor antagonist atosiban prolonged gastric emptying in healthy subjects and diabetic patients with gastroparesis lacked an elevation of the oxytocin plasma concentration postprandially compared to patients without gastroparesis." (PMID 22420866, 2012).
glioblastoma (1 paper, 2024). The most malignant astrocytic tumor (WHO grade IV). "Oxytocin receptor knockdown reduces the viability of glioblastoma U-87MG cells, and when these cells are treated with oxytocin, the expression of vimentin and drebrin, two cytoskeletal proteins, is increased." (PMID 39063232, 2024).
head and neck squamous cell carcinoma (1 paper, 2022). A squamous cell carcinoma that arises from any of the following anatomic sites: lip and oral cavity, nasal cavity, paranasal sinuses, pharynx, larynx, and salivary glands. "To further characterize the cell subset expressing OXTR in human OSCC, we first analyzed the correlation between OXTR and the genes differentially represented in a variety of tumor-associated cell populations in head and neck squamous cell carcinoma (HNSCC, n = 522, TCGA dataset, Firehose Legacy)." (PMID 36045118, 2022).
Hepatic steatosis (1 paper, 2025). Steatosis is a term used to denote lipid accumulation within hepatocytes. "OT treatment, on the other hand, has been reported to ameliorate hepatic steatosis and reduce triglyceride accumulation, potentially through hepatocyte OXTR signaling, which promotes autophagy and hepatocyte regeneration." (PMID 41160558, 2025).
Hypernatremia (1 paper, 2014). An abnormally increased sodium concentration in the blood. "The OXTR antagonist (AT; atosiban, 40 μg • kg−1 • h−1, i.v.; n = 7) and renal denervation (RX) reduced the renal vasodilation induced by hypernatremia." (PMID 25279805, 2014).
hyperprolactinemia (1 paper, 2021). Abnormally high level of prolactin in the blood. "Br treatment significantly decreased serum PRL levels and reversed OXTR-induced hyperprolactinemia." (PMID 34099636, 2021).
inflammatory bowel disease (1 paper, 2022). A spectrum of small and large bowel inflammatory diseases of unknown etiology. "In a separate inflammatory bowel disease (IBD) murine model, OXTR knock-out mice displayed an increased number of pro-inflammatory cytokine transcripts encoding for TNF-α, IL-1β, and IL-6 and exhibited shorter villi and crypts in the intestinal mucosa, a sign of chronic inflammation." (PMID 38983562, 2022).
intracerebral hemorrhage (1 paper, 2025). A cerebrovascular disorder characterized by bleeding into one or both cerebral hemispheres including the basal ganglia and the cerebral cortex. "In a mouse model of intracerebral hemorrhage, OXTR expression in the striatum is upregulated, suggesting that OXTR signaling may serve as a compensatory response to injury through stimulation by its ligand, OXT." (PMID 40635450, 2025).
irritable bowel syndrome (1 paper, 2009). Irritable bowel syndrome (IBS) is a chronic functional condition of the lower gastrointestinal (GI) tract characterized by abdominal pain or discomfort and disordered bowel habit (diarrhea, constipation, or fluctuation between the two). "Genetic variants in the OXT promoter region, and in the OXTR gene in DNA samples from 131 rigorously evaluated patients with Irritable Bowel Syndrome (IBS), 408 homozygous subjects referred for lactase (LCT-13910 C>T, rs4988235) genotyping, and 299 asymptomatic blood donors were compared." (PMID 19943975, 2009).
liposarcoma (1 paper, 2022). A usually painless malignant tumor that arises from adipose tissue. "In this study, we have made use of the liposarcoma cell line MLS-402, which was virally transduced to overexpress a fluorescently labeled OXTR." (PMID 36263085, 2022). "In this study we have made use of the human liposarcoma cell line MLS-402, which we tested for endogenous OXTR expression and found it to be below a reliable detection level using qPCR (Cq > 45, data not shown)." (PMID 36263085, 2022).
mastitis (1 paper, 2025). Inflammation of breast tissue during lactation or postpartum due to an obstructed duct or infection. "Inoculating mice with Clostridium tyrobutyricum protected against S. aureus-induced mastitis by activating the vagus nerve to release oxytocin (OT), which then inhibits the NF-κB signaling pathway by decreasing the production of oxytocin receptor (OTR) proteins." (PMID 41148692, 2025).
mastocytoma (1 paper, 2016). A localized tumor composed of sheets of mast cells without atypia. "We found that oxytocin receptor (OTR) was expressed in colonic mast cells in humans and rats, as well as in human mast cell line-1 (HMC-1), rat basophilic leukemia cell line (RBL-2H3) and mouse mastocytoma cell line (P815)." (PMID 27538454, 2016).
mesothelioma (1 paper, 2025). A usually malignant and aggressive neoplasm of the mesothelium which is often associated with exposure to asbestos. "Reduction of OXTR expression notably inhibited the proliferation of mesothelioma cell lines with high OXTR levels by disrupting the tumor cell cycle." (PMID 40362535, 2025). "Analysis of mesothelioma cell lines and The Cancer Genome Atlas (TCGA) data revealed a significant correlation between OXTR mRNA expression and NF2 gene inactivation." (PMID 40362535, 2025). "OXTR, upregulated in mesothelioma, is correlated with poor prognosis and represents a novel therapeutic target." (PMID 40362535, 2025). "Furthermore, OXTR antagonists reduced mesothelioma cell growth, and oral administration of the OXTR antagonist cligosiban hindered mesothelioma tumor progression." (PMID 40362535, 2025). "The oxytocin receptor (OXTR), a G-protein-coupled receptor, was recently significantly upregulated in mesothelioma cell lines compared with other cancer types." (PMID 40362535, 2025). "Emerging molecular targets in mesothelioma include mesothelin (MSLN), oxytocin receptor (OXTR), protein arginine methyltransferase (PRMT5), and carbohydrate sulfotransferase 4 (CHST4)." (PMID 40362535, 2025). "It has been demonstrated that OXTR expression is regulated by interleukin (IL)-6 and IL-1β, but the addition of these cytokines to mesothelioma cell lines with low OXTR expression did not markedly increase OXTR mRNA levels." (PMID 40362535, 2025).
Miscarriage (1 paper, 2024). A pregnancy that ends at a stage in which the fetus is incapable of surviving on its own, defined as the spontaneous loss of a fetus before the 22th week of pregnancy. "The study revealed that the group receiving oxytocin receptor antagonists exhibited significantly reduced rates of early miscarriage compared to the control group." (PMID 38997744, 2024).
mucopolysaccharidoses (1 paper, 2023). "As presented in this review, one of few molecular mechanisms of the effects of OXTR malfunctions in human diseases was reported in studies on mucopolysaccharidoses." (PMID 36835321, 2023). "Recent reports indicated that the changes in the levels of OXTR and the formation of its aggregates may influence the course of some inherited metabolic diseases, such as mucopolysaccharidoses." (PMID 36835321, 2023).
neuroblastoma (1 paper, 2025). Neuroblastoma (NB) is the most common solid, extracranial childhood tumor. "The impact of four common OXTR SNPs (rs1042778, rs4686302, rs2254298 and rs237887) on OXTR gene expression were tested in human neuroblastoma cell line, SH-SY5Y, a commonly used cell line for neurological disease." (PMID 39762756, 2025).
pancreas cancers (1 paper, 2022). "Furthermore, we observed a similar increase in OXTR expression in CAFs isolated from breast and pancreas cancers." (PMID 36045118, 2022).
pancreatic neuroendocrine tumor (1 paper, 2019). Pancreatic endocrine tumor, also known as pancreatic neuroendocrine tumor (PNET), describes a group of endocrine tumors originating in the pancreas that are usually indolent and benign, but may have the potential to be malignant. "In the gastrointestinal (GI) tract, a lesser number of small bowel and pancreatic neuroendocrine tumors (NETs) express OXT receptor (OXTR) gene, which is significantly different from the adjacent normal tissue." (PMID 31920487, 2019). "However, the absolute expression of OXTR in the NETs varies greatly according to the types of primary tumors and is close to the somatostatin receptor type 2 in the small bowel NETs but not in the pancreatic NETs." (PMID 31920487, 2019).